CXCL12 (C-X-C motif chemokine ligand 12)
Diseases named in the same sentence as CXCL12 in open-access papers (continued):
Sharing a sentence is not in itself a finding about the gene and the disease.
breast carcinoma (continued). "CAFs have been reported to recruit ECs and CD4+CD25+ T cells to the CSC niche in human breast cancer along the CXCL12/CXCR4 axis." (PMID 33530455, 2021). "In fact, in breast cancer patients lower CXCL12 expression levels correlated with worse prognosis, mirrored by higher levels of the ligand detected in breast cancer cell lines with a lower metastatic potential." (PMID 34834449, 2021). "Even more, C-X-C motif chemokine ligand 12 (CXCL12) stimulates H2O2 transport across the membrane by AQP3 in breast cancer cells MDA-MB-231 and DU4475." (PMID 33947079, 2021). "For instance, connexin 43-based gap junction, a channel connected between breast cancer and BMSCs, can be used to exchange microRNAs, thus suppressing the synthesis of CXCL12." (PMID 34712663, 2021). "We also showed that DPP-4 ablation in a primary mammary tumor induced tumor growth and metastasis via the CXCL12-mediated pathway." (PMID 34063285, 2021). "The CXCR4-targeted dendrimers encapsulating doxorubicin also reduce CXCL12-induced migration of BT-549 and T47D breast cancer cells." (PMID 33096815, 2020). "Taken together, our findings suggest that DPP-4 inhibitors potentiate chemotherapy resistance via the induction of ABC transporters by the CXCL12/CXCR4/mTOR/TGFβ signaling pathway in breast cancer cells." (PMID 31991851, 2020). "HGF and CXCL12 tumor expression appear to identify male breast cancer patients with a relatively good prognosis." (PMID 32188473, 2020). "A plethora of studies show that CXCR4, the chemokine receptor most commonly overexpressed in cancer, together with its natural chemokine ligand CXCL12 acts as a master regulator of breast cancer tumorigenesis." (PMID 33096815, 2020). "In our previous study, we have confirmed that DPP-4 inhibition induced the EMT through the CXCL12/CXCR4/mTOR axis in breast cancer." (PMID 31991851, 2020). "The CXCL12/CXCR4 signaling in breast cancer cells also induces resistance to immune checkpoint blockers." (PMID 33096815, 2020). "The hepatocyte growth factor (HGF)/c-MET axis and the stromal cell-derived factor-1 (CXCL12)/C-X-C chemokine receptor type 4 (CXCR4) axis are prognostic in women with breast cancer." (PMID 32188473, 2020). "Lung metastasis remains a significant cause of deaths in patients with breast cancer and the CXCR4/CXCL12 pathway is a key player in this process." (PMID 33096815, 2020). "ANGPTL2 and IL-6 enhance the reaction of breast cancer cells to bone-derived CXCL12 through the upregulation of CXCL12 receptor CXCR4 in these cancer cells, respectively." (PMID 33123472, 2020). "When LASP1 was stably knocked down in MDA-MB-231 (MDA-MB-231: ATCC® HTB-26TM, Manassas, VA, USA) breast cancer cells, there was an ablation of CXCL12-dependent invasion through Matrigel® (Matrigel: Discovery Labware, Inc., Bedford, MA, USA)." (PMID 32872485, 2020). "Several transcription factors have been reported to regulate the expression of CXCR4 and CXCL12 in breast cancer cells and those transcription factors can cooperate." (PMID 33096815, 2020). "In the present study, HGF and CXCL12 tumor expression identified male breast cancer patients with good prognosis." (PMID 32188473, 2020). "Another study showed that heregulin, a ligand for Erb3 and Erb4 receptors, sensitizes breast cancer cells for CXCL12 mediated Rac1 activation." (PMID 33096815, 2020). "For example, bone marrow stromal cells can transfer miR-127, miR-197, miR-222, and miR-223 to breast cancer cells via GJ channels, targeting CXCL12 expression, inhibiting cancer cell proliferation and impacting metastatic dormancy." (PMID 33066331, 2020). "The CXCL12/CXCR4 signaling is involved in extraversion of metastatic breast cancer cells in the liver." (PMID 33096815, 2020). "Although CXCL12/CXCR4 inhibition brings promising results in breast cancer trials, systemic effects of blocking CXCR4 such as alterations in the spleen remain poorly understood." (PMID 33096815, 2020).
breast carcinoma (continued). "Another study indicated that CXCR7/ACKR3 expression by breast cancer cells was down-regulated by MSC-derived CXCL12 (possibly due to ligand-dependent receptor internalization), and under these conditions, metastasis was reduced." (PMID 32582148, 2020). "The prognostic value of the CXCL12 expression in male breast cancer is comparable with the findings in female breast cancer reported in the literature." (PMID 32188473, 2020). "The pDC recruitment has been documented in human primary breast cancer, and the corresponding metastatic sentinel lymph nodes (SLNs) in response to CXCL12/SDF1, including only a minor fraction with a mature phenotype." (PMID 32054102, 2020). "The biological axis of CXCR4 and its receptor CXCL12 (Stromal cell‐derived factor‐1) promotes cancer cell growth, invasion and metastasis in most tumors including breast cancer." (PMID 32253815, 2020). "As previously discussed, the CXCL12 pathway is an important regulator of metastases in prostate, colorectal, and breast cancers." (PMID 32793401, 2020). "This prevents CXCL12-mediated CCL2 release from breast cancer cells and inhibits monocyte and mesenchymal stem cells recruitment and lung metastasis." (PMID 33096815, 2020). "The CXCL12/CXCR4 signaling pathway has emerged in the recent years as a key player in breast cancer tumorigenesis." (PMID 33096815, 2020). "CA breast cancer patients show higher CXCL12 expression than their AA counterparts, and this correlates with poor prognoses." (PMID 32824813, 2020). "For example, CCL2, CCL5, CXCL8, and CXCL12 can promote breast cancer, while CXCL9, CXCL10, and CCL16 can inhibit breast cancer." (PMID 32253815, 2020). "We show that the CXCL12/CXCR4 cascade is involved in nearly every aspect of breast cancer tumorigenesis including proliferation, cell motility and distant metastasis." (PMID 33096815, 2020). "In our previous study, we demonstrated that deficiency in DPP-4 induced EMT in 4T1 cells, MCF-7 cells and MDA-MB-231 cells and accelerated lung metastasis of breast cancer in vivo via the CXCL12/CXCR4/mTOR axis." (PMID 31991851, 2020). "Specifically, CXCL12 seems to play a detrimental role in breast cancer; its expression in patients has been extensively studied." (PMID 33096815, 2020). "TGF-β and CXCL12 secreted by CAFs enhances the metastatic potential of breast cancer cells undergoing incomplete EMT." (PMID 32546182, 2020). "Overall, several strategies to block CXCL12/CXCR4 signaling in breast cancer have been proposed including PPAR-γ agonists, dimerization with other receptors or chemokines and specific CXCR4 inhibitors including AMD3100." (PMID 33096815, 2020). "For example, heparin and Tinzaparin reduced the pulmonary metastasis of breast cancer cells that were over expressing CXCR4 by interfering with the interaction of CXCL12 and its receptor CXCR4." (PMID 32538273, 2020). "CAF-derived CXCL12 enhances the migration and invasion capacity of breast cancer cells and gastric cancer cells." (PMID 33050237, 2020). "In breast cancer brain metastases, the CXCL12/CXCR4 axis takes part in the homing, motility, and progression of metastases to regulate the migration of CTCs through the BBB." (PMID 32751846, 2020). "Dimerization seems to be another effective strategy to block the CXCL12/CXCR4 dependent migration in breast cancer." (PMID 33096815, 2020). "CXCL12 secreted by carcinoma-associated fibroblasts (CAFs) stimulates tumor growth directly, acting through CXCR4 expressed by breast cancer cells and promoting invasiveness." (PMID 33363463, 2020). "Members of the nuclear receptor superfamily such as estrogen receptor (ER) α and β also regulate the transcription of the CXCL12/CXCR4 cascade components in breast cancer." (PMID 33096815, 2020).
breast carcinoma (continued). "When coming to address the roles of CXCL12 in mediating tumor-stroma interactions in breast cancer, the majority of studies indicated that this chemokine or CXCR4 stand in the center of tumor-promoting cross-talks between cancer cells and stromal cells." (PMID 32582148, 2020). "In summary, CXCL12/CXCR4 signaling acts as a master regulator of breast cancer metastasis and mediates metastasis to all target organs such as brain, lungs, lymph nodes, liver and bones." (PMID 33096815, 2020). "High expression levels of CXCL12 were first described in ovarian tumors, later also in various solid tumor entities including breast cancer." (PMID 33013879, 2020). "The results suggested that CXCL9/10/13 expressions were significantly associated with infiltrating levels of B cells, CD8+ T cells, CD4+ T cells, neutrophils, and DCs in breast cancer, while CXCL12 was conversely correlated with macrophages." (PMID 32963527, 2020). "It is also interesting to note that CXCR4, another chemokine receptor, shows a higher expression in breast cancer tissue, whereas its ligand CXCL12 is downregulated in the same tissue, which is in contrast to the situation observed for CXCR2." (PMID 32727083, 2020). "Second, we suggest using diverse high-throughput technologies to evaluate the current status of CXCL12 signaling in patients with breast cancer during treatment." (PMID 33096815, 2020). "E-selectin allows the entry of breast cancer cells into the bone marrow, whereas the CXCL12/CXCR4 signaling anchors breast cancer cells in the microenvironment." (PMID 33096815, 2020). "First, we believe that computational approaches aiming to explore high-throughput data will generate novel basic knowledge about CXCL12/CXCR4 signaling in breast cancer." (PMID 33096815, 2020). "We have recently shown that a DPP-4 inhibitor accelerated the epithelial mesenchymal transition (EMT) and lung metastasis via the CXCL12/CXCR4/mTOR axis in breast cancer cells." (PMID 31991851, 2020). "The role of the CXCL12/CXCR4 axis in determining metastatic sites was first proposed in breast cancer." (PMID 32079335, 2020). "CXCR4 remains crucial in breast cancer metastasis pattern to the lungs, liver, bones and lymph nodes since these metastatic niches express high levels of its ligand CXCL12." (PMID 33096815, 2020). "CXCL12 in breast cancer is typically released from stromal cells, and in TNBC it is secreted by a specific immunosuppressive subset of fibroblasts." (PMID 33096815, 2020). "In breast cancer, the CXCL12-mediated effects on adaptive immunity are mainly detrimental and affect mostly T cells." (PMID 33096815, 2020). "Another aspect that supports a regulatory role of osteocytes during early stages of breast cancer bone metastasis is that osteocytes produce CXCL12, a chemokine involved in tumor cell homing and dormancy." (PMID 32092997, 2020). "This leads to the activation of the CXCL12/CXCR4 pathway in breast cancer cells supporting tumor cells stemness and growth in a paracrine manner." (PMID 33096815, 2020). "The heavy subunit of ferritin (FHC) has also been implicated in CXCL12-induced EMT and proliferation in breast cancer cells." (PMID 33096815, 2020). "We have shown that, depletion of fibroblast-specific CXCL12 results in reduced tumor growth, decreased number of CTCs and inhibits metastases of orthotopic and spontaneous mammary tumors." (PMID 33414786, 2020). "Network analysis on the cancer genome atlas (TCGA) breast cancer dataset revealed interaction between CXCL12 and CXCR7 (ACKR3), and a number of G-protein family members (GNG5, GNB4, GNB2, GNG12, GNG7, GNGT1, and GNAI3)." (PMID 30993013, 2019). "In these cells, H2O2 was produced in the extracellular space via Nox2 in response to CXCL12 stimulation, then rapidly transported into breast cancer cells through AQP3." (PMID 30893772, 2019). "It was reported that TCF12 enhanced CXCL12 secretion in CAFs to promote the growth of breast cancer cells." (PMID 31534521, 2019).
breast carcinoma (continued). "In breast cancer cells, CXCL12 leads to the phosphorylation of Cx43 through activation of protein kinase C. Thus, low levels of CXCL12 can downregulate Cx43 expression and its phosphorylation." (PMID 30805212, 2019). "The mechanism through which stromal RARβ achieves its tumor-promoting effect probably involves the production of CXCL12/SDF-1 in stroma cells and the consequent activation of the Src-ErbB2-Akt signaling pathway in the breast cancer cells." (PMID 31590252, 2019). "Significant correlation between CXCR7 and CXCL12 was also observed in the same patient cohort, suggesting a regulatory role for CXCR7 and CXCL12 in breast cancer biology." (PMID 30993013, 2019). "In fact, fibroblast growth factor, human growth factor, tenascin, thrombospondin-1, TGFβ and stromal cell-derived factor 1 (SDF-1 or CXCL12), are found in cancer cells including breast cancer, at sites of chronic inflammation produced by CAFs." (PMID 31430935, 2019). "Binding of the chemokine CXCL12 to its receptor CXCR4 stimulates downstream G protein signaling, leading to the activation of the PI3K/Akt or MAPK pathway, and the CXCL12/CXCR4 axis is a key step in breast cancer cell migration toward the lungs." (PMID 30893772, 2019). "It was shown in vitro that CAF-derived CXCL12 functions as an important EMT inducer in breast cancer cells by regulating the Wnt/β-catenin signaling pathway." (PMID 31106200, 2019). "Cxcl12 enhances anti-cancer immunity and thus blocks both metastasis and primary tumor growth particularly in breast cancer." (PMID 31534547, 2019). "Cytokines such as SDF-1 (CXCL12) produced by CAFs can also promote the proliferation of cancer cells carrying the SDF-1 receptor CXCR4; where SDF-1 expression-level correlates with breast cancer survival." (PMID 30927930, 2019). "In breast cancer models, SDF-1/CXCL12 is known to mediate the growth-promoting effects of stromal fibroblasts on cancer cells." (PMID 31861782, 2019). "Studies investigating breast cancer have found that the CXCL12/CXCR7 axis can serve as an intermediate link in the activation of endothelial cells." (PMID 31348616, 2019). "CXCL12 presentation was spatially controlled at the ventral side of breast cancer cells inducing lamellipodia and filopodia mediated by CXCR4." (PMID 31332163, 2019). "When CXCL12 expression was reestablished to normal levels, mammary carcinoma cells experienced reduced in vitro chemotaxis and in vivo metastasis leading to the proposal that CXCL12 silencing promotes mammary neoplastic transformations." (PMID 29682200, 2018). "In breast cancers with stromal fibroblasts that secrete SDF-1 and CXCL-12, the tumours exhibit increased growth, angiogenesis and invasion." (PMID 29098360, 2018). "This work exposes part of the complex interaction between CXCR4 and CXCL12 in PT, but also in metastases of a breast cancer model." (PMID 30012106, 2018). "As an important component of the chemokine family, the fibroblast-derived CXCL12 has been shown to play an important role in the development of various cancers such as breast cancer, lung cancer and thyroid cancer." (PMID 29305742, 2018). "TGF-β1 and SDF-1 (CXCL-12) and its G-protein-coupled transmembrane receptor, CXCR4, have been shown to be implicated in breast cancer and bone metastasis at many levels." (PMID 30150545, 2018). "Src is responsible for mediating breast cancer cell survival in the bone marrow, by controlling tumour cell response to both pro-survival signals in the bone microenvironment like CXCL12 and by conferring resistance to pro-apoptotic signals such as TRAIL." (PMID 29760166, 2018). "In summary, our results showed a different CXCR4 and CXCL12 pattern of expression in PT and metastases of cats with mammary carcinoma." (PMID 30012106, 2018). "While feline CXCR4 is significantly more expressed in PT, CXCL12 is highly abundant in distant metastatic organs such as liver and lung, as it has been observed for woman breast cancer." (PMID 30012106, 2018).
breast carcinoma (continued). "Luminal A (LA), luminal B (LB), normal and basal triple-negative (TN) tumors mimicked the trend of CXCR4 and CXCL12 expression previous described in PT, RM and DM of the total cohort of cats with mammary carcinoma." (PMID 30012106, 2018). "Our results indicate that TQ can down-regulate CXCR4 expression and CXCL12-induced migration and invasion in breast cancer cell lines through inhibition of NF-κB activation." (PMID 30564115, 2018). "This signaling axis also plays a critical part in breast cancer cell metastasis by increasing chemotaxis to regions of high CXCL12 expression such as bone, lung, and brain." (PMID 30564115, 2018). "In this study, we discovered a role for stromal-derived CXCL12 in breast cancer migration and invasion potentially through proteasome-mediated loss of mDia2 protein expression." (PMID 29596520, 2018). "We confirmed that 8 genes—MAPK14, CLOCK, NF2, HMGA2, CXCL12, E2F1, NOTCH1, and CD24—are associated with breast cancer." (PMID 30013305, 2018). "Remarkably, this compound has the capability to prevent VEGF-mediated tumor angiogenesis induced by the CXCR4/CXCL12 axis in breast tumor xenografts and exerts anti-metastatic activity in breast cancer in cultured cells and animal models." (PMID 30513833, 2018). "This role is exerted by H-ferritin via multiple mechanisms such as the regulation of CXCL12/CXCR-4 axis in breast cancer cells or the modulation of a specific microRNA pattern in ovarian cancer cells." (PMID 30518922, 2018). "CXCR4 was more expressed in PT than in metastases (p = 0.0067), whereas CXCL12 was highly expressed in metastatic lesions located in liver and lung (p < 0.0001), as reported for human breast cancer." (PMID 30012106, 2018). "For instance, the dimeric CXCL12 is more potent than monomeric CXCL12 in promoting β-arrestin 2 recruitment and chemoattractive activity in a model of human breast cancer." (PMID 29977203, 2018). "The results confirm our recent study where we found that cats with CXCR4 positive PT exhibit significantly lower serum CXCL12 levels than cats with CXCR4-negative mammary carcinomas." (PMID 30012106, 2018). "In particular, CXCL12 levels in bone marrow-derived mesenchymal stromal cells were found to be lower upon treatment with medium derived from breast cancer cells or in co-culture conditions." (PMID 29760166, 2018). "CXCL12 modulates cell proliferation, apoptosis, migration, and angiogenesis in various cancers including breast cancer." (PMID 30201690, 2018). "It has been shown that the elevated local expression of its ligand CXCL12 guides breast cancer cell trafficking to the lungs, brain, lymph nodes, liver, and bone marrow during the metastatic dissemination." (PMID 30591657, 2018). "In pre-clinical models, it has been demonstrated that ANGPTL2 strengthens responsiveness of breast cancer cells to chemokine (C-X-C motif) ligand 12 (CXCL12) by the up-regulation of chemokine (C-X-C motif) chemokine receptor 4 (CXCR4) in those cells." (PMID 29389861, 2018). "The discovery that cancer cells overexpress the chemokine receptor CXCR4 and that its blocking can inhibit metastasis to organs that express its ligand, the chemokine CXCL12, opened new therapeutic avenues for the targeting of metastatic breast cancer." (PMID 30441765, 2018). "Previous work identified a role for exogenous CXCL12 in breast cancer motility and migration, yet the source of CXCL12 influencing tumor motility was uncertain." (PMID 29596520, 2018). "Collectively, the inhibition of SOCE demonstrated decreased expression of high salt-induced release of inflammatory cytokine and chemokine, TNF-α and CXCL12, respectively, in the breast cancer cells MCF-7 and MDA-MB-231." (PMID 29861863, 2018). "Immunofluorescence and IHC have shown that CXCL12 is expressed most likely in the tumor cells and expression rates of 70.9%, 66.8% or 70.6% in breast tumors are relatively close to the CXCL12 expression obtained for feline mammary tumors in this study (78.1%)." (PMID 30012106, 2018).